TNF (tumor necrosis factor)
Diseases named in the same sentence as TNF in open-access papers (continued):
Sharing a sentence is not in itself a finding about the gene and the disease.
periodontitis (continued). "Higher levels of serum IL-6, C-reactive protein (CRP), TNF-α and IL-1β have been reported among periodontitis patients in several studies." (PMID 29980169, 2018). "The results of the study were demonstrative of increased IL-6, TNF-α, and visfatin levels in diabetic patients afflicted with periodontitis." (PMID 30186882, 2018). "Genetic analysis has revealed a large number of single nucleotide polymorphic (SNP) sites within the TNF-α locus that are related to periodontitis." (PMID 29449347, 2018). "Serum levels of proinflammatory cytokines such as IL-1β, IL-6, and TNF-α were increased in a rat ligature-induced periodontitis model." (PMID 29576800, 2018). "RA patients with periodontitis on DMARDs have been found to exhibit lower local IL-1β, IL-4, and TNF-α levels than otherwise healthy patients with periodontitis, however, the study about the effect of DMARDs on clinical periodontal parameters is limited." (PMID 30211216, 2018). "Five SNPs of TNF-α at promoter region (rs361525, rs1800629, rs1799724, rs1800630, and rs1799964) were genotyped by PCR-sequencing in periodontitis patients and control subjects." (PMID 29449347, 2018). "There are several contretemps regarding the TNF-α gene as a good candidate for genetic studies in relation to periodontitis." (PMID 29449347, 2018). "In this investigation, the periodontitis group showed higher salivary levels of IL-6 and TNF-α compared with periodontal healthy pregnant women." (PMID 29740515, 2018). "The purpose of this pilot study was to evaluate salivary levels of IL-6 and TNF-α according to periodontal status in pregnant women, in order to assess if the level of these pro-inflammatory cytokines could potentially be used as complementary diagnostic in pregnant women with periodontitis." (PMID 29740515, 2018). "In detail, IL-6 and TNF- α were only significantly increased in severe periodontitis compared to periodontal healthy groups." (PMID 29740515, 2018). "Alzheimer's patients showed high serum IL-6 levels while periodontitis patients had high serum TNF-α levels." (PMID 28959211, 2017). "This suggests that TNF-α is involved in osteocytic RANKL expression in type 1 diabetes with periodontitis." (PMID 29240821, 2017). "According to the obtained findings, salivary TNF-α and IL-1α levels were lower in patients with chronic periodontitis in comparison to control group." (PMID 29238418, 2017). "In patients with periodontitis and T2DM, increased TNF-α levels are associated with increased attachment loss." (PMID 28431542, 2017). "TNF-α is recognized as an important mediator in periodontitis and its levels are increased in gingival crevicular fluid (GCF) of patients." (PMID 29163477, 2017). "Local injection of a TNF antagonist in a periodontitis model results in diminished recruitment of inflammatory cells and periodontal destruction." (PMID 28264025, 2017). "Analysis of 12 CpG sites in the TNFα promoter in patients with chronic periodontitis and healthy controls revealed differences in DNA methylation only at one CpG site." (PMID 29201597, 2017). "Nal-P-113 exhibited protective effects on Porphyromonas gingivalis-induced periodontitis in rats by limiting the amount of bacteria and modulating IL-1β and TNF-α production." (PMID 28851350, 2017). "And a study with post-delivery women with periodontitis found an association between serum and GCF levels of TNF-α and PGE2." (PMID 29017560, 2017). "Comparison of mean TNF-α level between periodontitis and control groups before and after the treatment showed significant differences (P< 0.05)." (PMID 29238418, 2017). "Before starting treatment, salivary TNF-α and IL-1α concentrations were higher in healthy control group than in periodontitis group (P< 0.05)." (PMID 29238418, 2017). "TNF-α levels were significantly lower in those with moderate periodontitis compared with those who had severe periodontitis." (PMID 29109737, 2017).
periodontitis (continued). "The results showed that salivary TNF-α level was lower in periodontitis group compared to control group." (PMID 29238418, 2017). "Multiple proinflammatory cytokines in the gingival crevicular fluid (i.e., IL‐1, IL‐6 and TNF‐α) have been found to correlate closely with the status of periodontitis; this finding greatly benefits the diagnosis, treatment and prognosis of periodontal disease." (PMID 26932392, 2017). "The mean level of salivary TNF-α levels in the RA patients were(30.80 ± 26.73) pg/ml while in the chronic periodontitis patients and control subjects were (28.70 ± 35.24) pg/ml, (35.98 ± 30.43) pg/ml respectively." (PMID 28061876, 2017). "Many cytokines are involved in the process of periodontitis, including interleukins (ILs), tumor necrosis factor α (TNF-α), and interferon γ (IFN-γ)." (PMID 28640144, 2017). "The current study compared the periodontal parameters and the salivary level of TNF-α among RA patients, chronic periodontitis patients and healthy subjects." (PMID 28061876, 2017). "Patients with periodontitis and type 1 diabetes have higher expression levels of TNF-α than patients with periodontitis." (PMID 29240821, 2017). "Mean (SD) salivary TNF-α levels in periodontitis before and after the therapy and control group were 51.0 (17.7), 58.0 (15.33) and 72.4 (28.4) respectively." (PMID 29238418, 2017). "Our data indicate that TNF-α is involved in osteoclast formation in type 1 diabetes with periodontitis." (PMID 29240821, 2017). "Patients with periodontitis also displayed higher serum levels of IL-6 and TNF-α than the periodontally healthy individuals." (PMID 27111223, 2016). "Porphyromonas gingivalis in subgingival pockets is a major etiologic pathogen for periodontitis acting through the stimulation of host cells to produce inflammatory cytokines, including interleukin (IL)-1β, IL-6, IL-8 and tumor necrosis factor (TNF) α." (PMID 28030574, 2016). "Several pro-inflammatory cytokines are generally elevated during chronic periodontitis, TNF−α being amongst the most prominent." (PMID 27383471, 2016). "Interleukin‐6 (IL‐6) is secreted by various cell types and has been shown to be important pro‐ and anti‐inflammatory mediator involved also in the pathogenesis of periodontitis by regulating the expression of IL‐1 and tumor necrosis factor alpha (TNF‐α)." (PMID 29744169, 2016). "In inflammatory microenvironments, IL-1 and TNF have a prominent role in the pathogenesis of periodontitis." (PMID 27415426, 2016). "Serum levels of proinflammatory cytokines was also measured before periodontitis induction and they were higher in rats with dHPT (15.75 ± 0.49 vs. 10.12 ± 0.92 pg/m, for IL-1β and 176.75 ± 23.06 vs. 13.02 ± 1.38 pg/mL for TNF-α, p < 0.001)." (PMID 27617985, 2016). "The expression of TNFα was higher in periodontitis patients than healthy controls, and periodontal bacteria stimulate expression of TNFα." (PMID 27386246, 2016). "In Alzheimer’s Disease (AD) periodontitis may be even more common because of a reduced ability to take care of oral hygiene as the disease progresses and in AD increased elevation of serum levels of antibodies with associated increases in TNFα have been reported." (PMID 26963387, 2016). "Gingival tissues of chronic periodontitis patients exhibit significantly higher levels of pro-inflammatory cytokines IL-1, IL-6, IL-8 and TNFα than those of periodontally healthy patients." (PMID 27035339, 2016). "The increase in 11β-HSD1 mRNA in the ligature-induced periodontitis compared with the control was positively correlated with that in TNFα mRNA (p = 0.000 by significance testing of Pearson’s correlation coefficient)." (PMID 27716163, 2016). "The increase in the levels of 11β-HSD1 mRNA in the ligature-induced periodontitis compared with the control was positively correlated with that of TNFα mRNA." (PMID 27716163, 2016).
periodontitis (continued). "The expression of TNFα mRNA in periodontal tissues was concurrently examined to confirm the induction of periodontitis by ligature placement." (PMID 27716163, 2016). "THSG and resveratrol both inhibited the expression of proinflammatory cytokines such as IL-1β and TNF-α, which are involved in pathogenesis of periodontitis." (PMID 27504055, 2016). "In our study, we observed that the serum TNF-α levels of diabetic mice were higher compared to their normal controls, and the diabetic periodontitis mice showed higher serum TNF-α levels than those of C57 mice in the infection group." (PMID 27995146, 2016). "TLR-2 and TLR4 play critical roles in recognizing periodontal pathogens and trigger the up-regulation of interleukin (IL)-6, IL-1β, and tumor necrosis factor (TNF)-α in periodontitis." (PMID 27529418, 2016). "Cluster 5 genes (n = 34) showed a positive correlation with MMP9, RANKL, and CTSK in both healthy and periodontitis tissues, and a positive correlation with TNFα, but only in the healthy tissues." (PMID 27486459, 2016). "Periodontitis is an inflammatory disease in which higher expression of TNF-α, IL-1β and LPS were found in the periodontal microenvironment in patients." (PMID 27216891, 2016). "Higher levels of circulating TNF-α in patients with periodontitis as compared with healthy subjects have consistently been reported in most studies." (PMID 26644840, 2015). "The systemic levels of TNF-α in subjects with periodontitis and the impact of periodontal treatment on serum TNF-α concentrations are little understood." (PMID 26644840, 2015). "Significant inhibitory effects of IL-1 and TNF antagonists on periodontal inflammatory and destructive responses have been demonstrated in a Macaca fascicularis primate model of experimental periodontitis." (PMID 25657893, 2015). "MMPs and local levels of inflammatory mediators such as Interleukin 1beta (IL1-ß), Interleukin 8 (IL-8) and Tumor necrosis factor alpha (TNF-α) were also found to be elevated in periodontitis as well as in infectious lung diseases." (PMID 26656474, 2015). "The objective of this study was to assess the serum levels of adiponectin, leptin and TNF-α of periodontally healthy normal weight (NW) patients, NW patients with chronic periodontitis (CP), periodontally healthy obese patients and obese patients with CP." (PMID 26330934, 2015). "The study participants consisted of 20 patients with RA and periodontitis who were treated with TCZ and 40 patients with RA and periodontitis who received medication with tumor necrosis factor inhibitor (TNFI)." (PMID 29744142, 2015). "To date, there have been several studies evaluating in vitro and in vivo efficacy of TNF-α- and IL-6R-targeted therapies in the treatment of periodontitis." (PMID 25657893, 2015). "In serum, significant concentrations of IL-6 and TNF-α were present during the evolution of periodontitis and reactional lesions, while IFN-γ and IL-1β were related with T1R, T2R, and CPD." (PMID 26339136, 2015). "TNF-α, a cytokine with some functions similar to those of IL-1β, has been detected at sites affected by periodontitis TNF-α and IL-1β act synergistically to initiate the cascade of inflammatory mediators." (PMID 25888355, 2015). "Among cytokines, IL-1β and TNF-α are essential in the development and progression of periodontitis, as it has been shown that their antagonists inhibit the inflammatory response in experimental PD." (PMID 25587321, 2014). "Clinical studies have shown an upregulation of TNF-α in periodontitis, e.g., in gingival crevicular fluid, in gingival tissues, and in plasma and serum." (PMID 25179218, 2014). "Elevated TNF-α levels in infected root canals, gingival crevicular fluid and saliva of patients with aggressive periodontitis has been reported to stimulate osteoclast generation through the induction of M-CSF." (PMID 24970360, 2014).
periodontitis (continued). "This study aimed at evaluation of pro-inflammatory cytokine response (TNF-α, IL-1β and IL-17) in patients with chronic periodontitis administered per os with a probiotic strain of Lactobacillus reuteri." (PMID 24509697, 2014). "It has been reported that IL-1 and TNF-α antagonists inhibit the inflammatory responses and bone destruction in experimental periodontitis." (PMID 25610476, 2014). "Substances such as C-reactive protein (CRP), aspartate amino transferase (AST), tumor necrosis factor-alpha (TNF-α), and prostaglandin (PG) E2 have been extensively assayed for periodontitis leading to other subclinical infection." (PMID 24692844, 2014). "High levels of TNF-α have been identified in the tissue and gingival crevicular fluid of patients with advanced periodontitis and chronic periapical periodontitis." (PMID 24970360, 2014). "It has been shown that of TNF-α is upregulated in periodontitis, e.g., in gingival crevicular fluid and in gingival tissues." (PMID 25179218, 2014). "CBD treatment inhibits the progression of periodontitis that was accompanied by a decrease in neutrophil migration, expression of bone related molecules and production of IL-1β and TNF-α." (PMID 25517414, 2014). "Tissue destruction in periodontitis results from the inflammatory response to the microbial products and cytokines including IL-1β and TNF- α." (PMID 25587321, 2014). "If periodontitis can lead to the elevation of CRP & TNF-α levels, then theoretically, periodontal therapy should help in reducing the systemic burden of inflammation." (PMID 24198887, 2013). "In conclusion, the levels of three cytokines (TNF-α, IL-6 and IL-8) in the human gingival tissues of 19 patients with periodontitis were detected by ELISA." (PMID 24137277, 2013). "The present study was envisaged to determine the influence of periodontal treatment on the serum CRP & TNF-α level in cardiovascular patients with periodontitis." (PMID 24198887, 2013). "In the present study, we confirmed that macrophages densely expressed TLR2, TLR4, TNF-α, and iNOS in the gingival tissues of chronic periodontitis patients." (PMID 24363500, 2013). "The levels of IL-6, IL-8 and TNF-α have been observed to be elevated in chronically inflamed gingival tissues, as well as in the gingival crevicular fluid from patients with periodontitis." (PMID 24137277, 2013). "Consistent with other inflammatory diseases, proinflammatory cytokines, including IL-6, IL-8 and TNF-α, appear to be major mediators in periodontitis." (PMID 24137277, 2013). "The expression of Toll-like receptor 2 (TLR2), TLR4, TNF-α, and inducible NO synthase was mainly detected in the gingival macrophages of chronic periodontitis patients." (PMID 24363500, 2013). "Clinical parameters such as OHI-S index and PPD showed a positive correlation with CRP & TNF-α level in both the groups with chronic periodontitis in this study." (PMID 24198887, 2013). "Other studies show spontaneous osteoclast formation and increased bone resorption from circulating PBMCs of periodontitis patients correlating with high levels of TNF-α and RANK-L." (PMID 23762091, 2013). "Experimental model of periodontitis in primates demonstrates that local injections of TNF-α antagonists reduce the appearance of inflammatory cells in the alveolar bone and the formation of bone resorbing osteoclasts." (PMID 23762091, 2013). "The aim of the present study was to quantify IL-6, IL-8 and TNF-α levels in the human gingival tissues of patients with periodontitis and to assess the correlation of these three cytokines with each other." (PMID 24137277, 2013). "The aim of the current study was to quantify IL-6, IL-8 and TNF-α levels and assess the correlation of these inflammatory markers in the human gingival tissues of patients with periodontitis." (PMID 24137277, 2013).
periodontitis (continued). "A panel of 8 SNPs in VEGF, ACT, HMG-CR, INF-γ, IL-1β, IL-10, IL-6 and TNF-α genes in patients with periodontitis and controls (CTR) was studied and genotype distributions and allele frequencies were obtained." (PMID 24274085, 2013). "For TNF-α, although there was an expression downtrend, the immunoreactive cell number was still higher in the stress group than in the periodontitis group at week 2 and week 4 (P < 0.05)." (PMID 23326020, 2012). "In the natural healing process of periodontitis, the expression of IL-1β and TNF-α reduced markedly." (PMID 23326020, 2012). "The aim of this study is to compare genotypes and soluble protein of pro and anti-inflammatory cytokines (IL-1α, IL-1β, IL-6, IFN-γ, IL-10, TNF-α and IL-4) in subjects with or free of chronic periodontitis." (PMID 23046796, 2012). "It showed that both the IL-1β/bFGF ratio and TNF-α/bFGF ratio were highest at baseline in periodontitis and periodontitis/stress group." (PMID 23326020, 2012). "After ligature removal, the expression of IL-1β and TNF-α significantly decreased in the periodontitis group at week 1, 2, and 4 compared with baseline level (P < 0.05)." (PMID 23326020, 2012). "In the gingival crevicular fluid, elevated IL-6, TNF-α, and IL-1β were reported in persons afflicted with periodontitis." (PMID 22315682, 2012). "High levels of several inflammatory cytokines, such as IL-1α, IL-1β, IL-6, interferon-γ (IFN-γ), and tumor necrosis factor α (TNF-α), have been found in the tissue and gingival crevicular fluid of patients with advanced periodontitis." (PMID 22485170, 2012). "The periodontitis healing condition was assessed, and the expression of interleukin-1β (IL-1β), tumor necrosis factor-α (TNF-α), and bFGF were tested by immunohistochemistry." (PMID 23326020, 2012). "Studies also have shown that when periodontitis exists, some inflammatory cytokines, such as IL-1β and TNF-α, are significantly increased in periodontal tissue, gingival crevicular fluid, or peripheral blood." (PMID 23326020, 2012). "Statins also reduce the production of IL-1β and TNFα, inflammatory cytokines which are known to play a pivotal role in periodontitis." (PMID 22203908, 2011). "Several reports have suggested a relationship between the progression of periodontitis and the expression of interleukin-1 (IL-1), IL-6, IL-8, and tumor necrosis factor-α in gingival tissues." (PMID 22131647, 2011). "The proinflammatory cytokine TNFα is also reported to play an important part in the pathogenesis of periodontitis." (PMID 20398340, 2010). "The present experiment is performed to study the role of RANTES and the cytokine TNF-α expression in human gingival tissues with chronic periodontitis and CsAinduced gingival overgrowth compared with normal healthy gingival tissues." (PMID 20871770, 2010). "We confirm that the model of periodontitis used here leads to a substantial increase in the levels of TNF-α and IL-1β in the gingivomucosal tissue." (PMID 21253492, 2010). "zeae N165 cells significantly reduced alveolar bone resorption, TNF-α, and IL-6 levels in rats with periodontitis, maintained a healthy oral and intestinal microbial community structure, and regulated the dominant species to alleviate periodontitis." (PMID 41635731, 2026). "Chronic inflammation in periodontitis and gingivitis reflects an imbalance between pro-inflammatory and anti-inflammatory signaling, driven by elevated pro-inflammatory cytokines and chemokines, such as IL-6, TNF-α, and IL-1β." (PMID 41516397, 2026). "Furthermore, as a major pro-inflammatory factors, tumor necrosis factor-alpha (TNF-α) significantly increases in the gingival crevicular fluid of periodontitis patients." (PMID 40083664, 2025). "Furthermore, inflammatory cytokines, such as C-reactive protein, tumor necrosis factor-α, immunoglobulin G, interleukin-1β, and interleukin-6, are released in response to periodontitis." (PMID 40907543, 2025).